FDX1 (ferredoxin 1)
Diseases named in the same sentence as FDX1 in open-access papers (continued):
Sharing a sentence is not in itself a finding about the gene and the disease.
cancer (continued). "To summarize, FDX1 functions as a crucial regulator of cuproptosis, impacting cancer tumor progression, prognosis, immune infiltration, and therapeutic responses." (PMID 40589743, 2025). "FDX1 is predominantly downregulated in various types of cancer tissues, particularly in solid tumors, including clear cell renal cell carcinoma (ccRCC), breast invasive carcinoma, colon adenocarcinoma, lung adenocarcinoma, thyroid carcinoma, and HCC." (PMID 40341098, 2025). "FDX1 has been discovered to own important roles to participate into various cancers’ progression through acting as a suppressor." (PMID 38520567, 2025). "FDX1-dependent cancer cells require lipoic acid pathway components for survival, and modifications reduce metabolic enzyme lipoylation, making some cells susceptible to elesclomol-induced cuproptosis." (PMID 38835782, 2024). "Recent analysis indicated that expression of cuproptosis-induced FDX1 negatively correlates with numbers of CD4 + T cells and cancer-associated fibroblasts (CAFs) infiltration." (PMID 39068453, 2024). "For example, sorafenib, the first multi-tyrosine kinase inhibitor approved for diverse cancers and known to induce ferroptosis, has been found to enhance cuproptosis by increasing FDX1 aggregation and GSH depletion." (PMID 38918694, 2024). "Several databases examining FDX1 expression in human cancers have identified FDX1 as a prognostic biomarker for pan-cancer." (PMID 38802900, 2024). "FDX1 exhibits reduced expression in various cancer types and exhibits significant correlations with clinical parameters, TMB, MSI, and immune‐associated pathways." (PMID 38898987, 2024). "In summary, these studies depict a close connection between FDX1 and clinical characteristics, anticancer drug sensitivity, immune-related pathways, and immune cell infiltration in various cancer types." (PMID 38918694, 2024). "Previous studies have shown a connection between the toxicity of elesclomol in cancer cells and many parameters, such as the levels of ferredoxin-1 and the rates of mitochondrial respiration, which are influenced by the availability of Cu." (PMID 38835782, 2024). "In summary, FDX1-oriented cuproptosis regulates the propagation of diverse cancers; hence, targeting FDX1 is a strong candidate for cancer treatment." (PMID 39329964, 2024). "In conclusion, our results indicated that the expression of FDX1 related to patients' prognosis and immune cell infiltration in different type of cancers." (PMID 37193786, 2023). "Following our demonstration of differential FDX1 expression in different immune subtypes, an analysis of FDX1 and immune cell infiltration in human cancer was carried out." (PMID 37193786, 2023). "The result revealed that FDX1 was low expressed in most cancers, such as BRCA, KICH, KIRC, LUAD, LUSC, PCPG, and THCA; as well as COAD." (PMID 36173462, 2023). "In the present study, we conducted a comprehensive analysis to examine the role of FDX1 in human cancer prognosis and immunology." (PMID 37193786, 2023). "Meanwhile, the correlations between FDX1 expression and survival rate and its effect on different functional states of cancer cells were also analyzed." (PMID 36173462, 2023). "By using the BioGPS database, we investigated the expression of FDX1 in different normal tissues and cancer cell lines, and found that almost all cancer cell lines expressed FDX1." (PMID 37193786, 2023). "We also found FDX1 was differently negatively expressed in the cancers ACC and STAD but positively expressed in LGG and TGCT in the stromal score." (PMID 37298135, 2023). "Prospective studies of FDX1 expression and its role in immune infiltration of cancer are needed in the future." (PMID 37193786, 2023). "A pan-cancer analysis of FDX1 was recently conducted, and it was demonstrated that FDX1 was significantly associated with immune-related pathways." (PMID 37123026, 2023).
cancer (continued). "Regarding RNA modification, we found that m1A, m5C, and m6A led to a positive effect on FDX1 expression across nearly all cancer types, except TGCT, DLBC, ESCA, PCPG, CHOL, LIHC, and UCS." (PMID 36766692, 2023). "Oppositely, FDX1 expression was negatively correlated with that of CD4+ T cells and cancer-associated fibroblasts (CAFs)." (PMID 36173462, 2023). "Our study showed that MRPL13 and its associated genes were significantly correlated with cuproptosis-related genes across cancers, with the most significant ones being FDX1, GCSH, DLST, and DLD." (PMID 37827692, 2023). "In line with previous studies, the expression of FDX1 was significantly lower in most cancer types, except GBM, STAD, DLBC and THYM10–14." (PMID 37193786, 2023). "Some studies have deciphered the mechanism of ROS induced by FDX1 in cancer cells, which is a unique mode of action dependent on its copper chelating ability." (PMID 37152642, 2023). "Based on the results presented above, it appears that FDX1 genomic changes and differential expression are indeed found in cancer tissue, and possibly play a role in cancer progression and onset." (PMID 37193786, 2023). "In this study, we systematically elaborated on the expression levels, prognostic impact, and biological function of CDRs and FDX1 in diverse cancer types." (PMID 36766692, 2023). "Pathway analysis revealed that the expression of FDX1 was correlated to cancer-related and immune-related pathways." (PMID 37193786, 2023). "High FDX1 expression differed in immune and molecular subtypes within multiple human cancers and was highly expressed in the LIHC, STAD, KIRC, and PRAD of the immune subtypes." (PMID 37298135, 2023). "The data also demonstrated that the level of FDX1 was closely correlated with distinct pathological stages in patients with multiple cancer types." (PMID 37298135, 2023). "To determine its potential mechanism of action, we studied FDX1 expression in different immune subtypes and molecular subtypes of human cancers." (PMID 37193786, 2023). "In pan-cancer analysis, as a key regulator in copper-induced cell death, the transcription and protein expression of FDX1 were significantly reduced in most cancer types." (PMID 37318594, 2023). "The results of the analysis demonstrate a strong association between FDX1 expression and immune cell infiltration in the TME across multiple cancer types." (PMID 37298135, 2023). "The result indicated that the FDX1 level significantly increased in cancer-initiating stem cells, and it functions in cancer resistance." (PMID 37298135, 2023). "FDX1 regulation with a combination of immuno-checkpoint inhibitor therapy and chemotherapy drugs to promote the antitumor immunotherapy of multiform cancers will contribute to our development of antitumor drugs in the future." (PMID 37298135, 2023). "The objective of this study was to evaluate the potential of FDX1 in anticancer immunotherapy in human cancer, offering insights into a novel approach to cancer treatment." (PMID 37193786, 2023). "The knockout of FDX1 resulted in cancer cells becoming sensitive to the copper ion concentration, conversely, the knockout of CDKN2A improved the tolerance of cancer cells to copper ion." (PMID 37538124, 2023). "According to the TCGA and GTEx datasets, FDX1 expression differs significantly between multiple cancer types, which indicates that FDX1 level is closely related to patients’ clinical prognosis." (PMID 37298135, 2023). "Based on the results above, it appears that the expression of FDX1 has a significant clinical prognostic value in certain types of cancer." (PMID 37298135, 2023). "FDX1's dual role in cuproptosis and cancer biology increases the likelihood of identifying novel therapeutic targets and prognostic biomarkers through its study." (PMID 37193786, 2023). "We used the GEPIA, TIMER and BioGPS databases to analyze the levels of FDX1 expression in cancers and normal tissues as a first step in our study." (PMID 37193786, 2023).
cancer (continued). "Inhibitors of FDX1 or LIAS have been studied for their anti-cancer activity, and have shown promising results in preclinical studies." (PMID 37564178, 2023). "SKCM cancer showed high FDX1 expression via Western blotting (Beyotime, Shanghai, China) and RT-qPCR (Novoprotein, Shanghai, China)." (PMID 37298135, 2023). "We explored the different expressions of FDX1 in various types of cancers from the TIMER2.0 of TCGA databases." (PMID 37298135, 2023). "We also identified relevant gene set pathways of FDX1 through the GSEA tool in multiple types of cancer." (PMID 37298135, 2023). "FDX1 expression was significantly associated with a better prognosis for survival in ESCA, KICH, LIHC, and THCA cancers." (PMID 37298135, 2023). "FDX1 was significantly negatively expressed in the cancers ACC and THCA in the immune score, but we found it to have a positive correlation with PCPG, SARC, and LGG." (PMID 37298135, 2023). "FDX1 expression in different immune and molecular subtypes of human cancers was evaluated using the TISIDB database." (PMID 37193786, 2023). "By using the TISIDB website, we investigated the role of FDX1 expression on immune and molecular subtypes in human cancers." (PMID 37193786, 2023). "The highest alteration frequency in FDX1, including mutation, amplification, and deep deletion, existed in UCS cancer patients." (PMID 37298135, 2023). "Further, analysis of the Cancer Dependency Map Portal (DepMap) revealed that SLC27A5 exhibited a significant co-dependency with FDX1 (r = 0.19, p = 1.7e-10)." (PMID 38157255, 2023). "We found strong relationships between 47 ICP genes and FDX1 expression in several cancer types, except CHOL, ESAD, ESCC, MESO and UCS." (PMID 37193786, 2023). "In our study, we explored the role of FDX1 in TCGA human pan-cancer including clinical and immunological characteristics." (PMID 36825202, 2023). "Prognostic analysis for OS, DSS, and PFS revealed that hypomethylation of DLAT, FDX1, MTF1, NLRP3, and PDHA1 was associated with low survival in most cancers, whereas hypermethylation of FDX1 and PDHB was associated with low survival in UVM(P < 0.05)." (PMID 36387247, 2022). "We further explored the expression level of FDX1 in Pan-cancer, which showed that HCC tissues expressed higher FDX1 than the majority of cancer types." (PMID 36408192, 2022). "In some cancer types, FDX1 expression was also markedly correlated with the clinical characteristics, TMB, MSI, and antitumor drug susceptibility or resistance of different tumors." (PMID 35991547, 2022). "The results showed that cuproptosis-related genes such as PDHB, PDHA1, DLAT, DLD, LIPT1 were significantly positively correlated with FDX1 in pan-cancer." (PMID 35991547, 2022). "The mRNA level obtained from TCGA database showed that FDX1 in normal tissues adjacent to cancer was higher than in the cancer tissues." (PMID 36105937, 2022). "To better understand FDX1 expression in various cancer types, we first analyzed its expression in 33 cancers using TCGA data." (PMID 36210836, 2022). "The pan-cancer analysis showed that FDX1 was significantly downregulated and closely related to prognosis in ccRCC among 33 cancer types." (PMID 36536785, 2022). "Tsvetkov also found that FDX1 was a direct target of elesclomol, which promotes copper-dependent cell death in cancer cells." (PMID 36092887, 2022). "This study revealed the survival predictive value and potential immunotherapy value of FDX1 in pan-cancer with comprehensive analyses." (PMID 35991547, 2022). "Pan-cancer analysis showed that the high expression of FDX1 served as a good prognostic factor in some cancers (HR < 1)." (PMID 36105937, 2022). "The results based on the CancerSEA database showed that FDX1 is closely related to differentiation, proliferation, stemness, and invasion at the single-cell level in most cancers." (PMID 36210836, 2022).
cancer (continued). "Next, we used the PPI network, the CancerSEA database, and GSEA analysis to address the function of FDX1 in pan-cancer specifically." (PMID 36210836, 2022). "The differential expression of FDX1 was significant in ccRCC compared with that in other cancer types (p = 2.63E–39)." (PMID 36186457, 2022). "Here, bioinformatics analyses were conducted to evaluate different FDX1 expressions in tissues and their possible link with cancer." (PMID 36061184, 2022). "FDX1 can be used as a new prognostic marker for various malignancies and an indicator of cancer immunotherapy response." (PMID 36061184, 2022). "To investigate the difference in FDX1 expression in cancer cell lines, we obtained the mRNA and proteomic data of various cancer cell lines from DepMap." (PMID 36186457, 2022). "Using univariate Cox regression analysis, we used data from the TCGA database to assess the correlation between the respective expression levels of FDX1 and OS in various cancers." (PMID 36061184, 2022). "The results showed that in the TME of many cancers, FDX1 had a good correlation with various types of immune cell invasion (CD4+ T cells, Macrophages, B cells, T cells regulatory, Mast cells resting, etc.)." (PMID 35991547, 2022). "Our results revealed that FDX1 expression was correlated with the functional state of stemness, invasion, differentiation, proliferation, metastasis, and DNA damage in several cancers." (PMID 36210836, 2022). "Our data showed that FDX1 expression was negatively correlated with drug sensitivity in most cancers, such as AT−7519, KIN001−102, NPK76−II−72−1, PIK−93, Phenformin, and XMD13−2." (PMID 36210836, 2022). "In this study, transcriptome expression datasets and related clinical features were acquired from The Cancer Genome Atlas (TCGA) to investigate FDX1 altered expression and prognosis in pan-cancer and ccRCC." (PMID 36186457, 2022). "Upregulation of this checkpoint gene is associated with escape mechanisms in the immune microenvironment, which suggested that FDX1 plays a role in different immunomodulatory effects in various cancer types." (PMID 36061184, 2022). "FDX1 has been reported to enhance the copper-dependent cell death induced by elesclomol, providing a new idea to improve the efficacy of cancer-targeted drugs." (PMID 36387247, 2022). "Our study found that the gene and protein levels of FDX1 were significantly lower in most tumors and had certain prognostic value in some cancers." (PMID 35991547, 2022). "Taken together, the data suggest that FDX1 provides a valuable new biomarker for several cancers for assessing prognosis and immunotherapy response." (PMID 36061184, 2022). "The protein levels of FDX1 in different cancers showed that expression of FDX1 decreased in solid tumors such as HNSC, KIRC, COAD, LUAD, LIHC, PAAD." (PMID 35991547, 2022). "Consistent with our data, FDX1 was previously reported to be involved in cell proliferation and thus resulted in cancer development." (PMID 36210836, 2022). "We also verified this result at the protein level, where the expression of FDX1 was downregulated in Caki-1, 786-O, and 769-P cancer cell lines and 6 paired ccRCC tissues using Western blotting analysis." (PMID 36536785, 2022). "Our findings suggested that FDX1 generally correlated with many important pathways in cancer formation." (PMID 35991547, 2022). "It has been reported that FDX1 can enhance the copper-dependent cell death induced by elesclomol and can offer new ideas to improve the efficacy of several cancer-targeted drugs." (PMID 36061184, 2022). "Our analysis indicated that FDX1 had potential value for predicting chemotherapy sensitivity, but its relationship with drug sensitivity varied by cancer types." (PMID 36226187, 2022). "Next, we evaluated the prognostic value of FDX1 expression in pan-cancer, including OS, DSS, DFI, and PFI analyses based on the TCGA database." (PMID 36210836, 2022).
cancer (continued). "The correlation between FDX1 and immunoinfiltrating cells in 33 kinds of cancers in the TIMER database was investigated." (PMID 36061184, 2022). "For immune-regulatory genes and chemokines, the gene co-expression of FDX1 showed significant heterogeneity in different types of cancer, but there was an interesting consistency in the immune gene level." (PMID 35991547, 2022). "RCC exhibited a relatively low expression below the dashed lines, which indicated the median expression value of FDX1 mRNA of all cancer cell lines." (PMID 36186457, 2022). "When we combined data from TCGA and GTEx databases, we found that the expression of FDX1 was highly different in 26 cancers." (PMID 36210836, 2022). "The results showed FDX1 was downregulated in Caki-1, 786-O, and 769-P cancer cell lines and 38 paired ccRCC tissues when compared with normal cells or tissues." (PMID 36536785, 2022). "In this study, we provide a comprehensive pan-cancer analysis of FDX1 and have shown that the distinct expression of FDX1 correlates with the survival outcome of patients with diverse cancers." (PMID 36605188, 2022). "To determine the expression profile of FDX1 in all 33 TCGA cancer types, we performed TCGA analysis of FDX1 mRNA expression levels measured by log2 TPM (Transcripts Per Kilobase Million) in the RNA-seq database." (PMID 36186457, 2022). "Cancer types with high FDX1 expression (KIRC, THYM) showed a favorable prognosis compared with the low expression group as learned from the later survival analysis." (PMID 36061184, 2022). "In this study, we integrated a series of public bioinformatic analysis to explore the mRNA and protein profiles of FDX1 across human cancers and cell lines and validated its expression and prognostic value, especially in ccRCC." (PMID 36186457, 2022). "The expression of FDX1 was positively correlated with the infiltration level of CD8+T cells, NK cells and neutrophil cells but negatively correlated with CD4+T cells and cancer associated fibroblasts." (PMID 36523779, 2022). "Through bioinformatic data mining in 33 types of TCGA cancer, we found that FDX1 mRNA expression was significantly downregulated in ccRCC." (PMID 36186457, 2022). "It was found that FDX1 was also well correlated with many cellular redox signaling-related genes in pan-cancer, for example, most genes in LGG and DLBC were significantly negatively correlated with FDX1 but positively correlated in UVM and SKCM." (PMID 35991547, 2022). "An in-depth understanding of FDX1-regulated cuproptosis in KIRC will help enable a new way to kill cancer cells by exploiting the distinct action of copper." (PMID 36292610, 2022). "To acquire comprehensive prognostic values of FDX1 in pan-cancer, we used the TCGA and GEO datasets to present the correlation between FDX1 expression and prognosis." (PMID 36186457, 2022). "In this study, we explored the expression and prognostic value of FDX1 in numerous types of cancer and identified its characteristic role in ccRCC using a series of online bioinformatic databases." (PMID 36186457, 2022). "The heatmap profiled the correlations between FDX1 expression and the infiltration of 28 immune cell types across human cancers." (PMID 36186457, 2022). "Most cancers show significantly lower mRNA levels in FDX1, DLD, DLST, LIAS, GLS, DBT, MTF1, and PDHB." (PMID 36209249, 2022). "In brief, they found that elesclomol binds and inhibits FDX1, leading to copper‐dependent cell death in those proteotoxic stress‐resistant cancer cells." (PMID 34390123, 2021). "Modulating the expression of FDX1 may represent a promising strategy to enhance the efficacy of treatments designed to induce cuproptosis in cancer cells, potentially leading to novel therapeutic approaches in oncology." (PMID 40589743, 2025). "Further investigation into the mechanisms and interactions of FDX1 could reveal new pathways for targeted therapies in both cancer and age-related diseases." (PMID 40589743, 2025).